SMIM18 (small integral membrane protein 18)
Tractability: Antibody: UniProt predicts a signal peptide or a membrane-spanning region.
Gene: Protein-coding gene on chromosome 8 (30,638,576 to 30,647,260, forward strand). Ensembl gene ENSG00000253457.
Subcellular location: Membrane
Subcellular location (Human Protein Atlas): Nucleoplasm; Centrosome
Gene Ontology:
Cellular component: membrane
Genetic constraint (gnomAD): Loss-of-function variants: 4 observed, 6.23 expected, observed/expected ratio (o/e) 0.64, 90% interval 0.31 to 1.44. That is too few expected variants to judge how well the gene tolerates losing a copy. Missense variants: 89 observed, 115.5 expected, observed/expected ratio (o/e) 0.77, 90% interval 0.65 to 0.92. Synonymous variants: 37 observed, 39.49 expected, observed/expected ratio (o/e) 0.94, 90% interval 0.72 to 1.23.
Homologues: Orthologues: pig SMIM18 (97% identical), rat Smim18 (97% identical), dog SMIM18 (96% identical), guinea pig SMIM18 (95% identical), rabbit SMIM18 (94% identical), mouse Smim18 (89% identical), tropical clawed frog smim18 (65% identical), zebrafish smim18 (41% identical).